MET (MET proto-oncogene, receptor tyrosine kinase)
Diseases named in the same sentence as MET in open-access papers (continued):
Sharing a sentence is not in itself a finding about the gene and the disease.
cancer (continued). "Thus, several studies already use antibodies such as rilotumumab or onartuzumab to inhibit HGF/MET in different types of cancer." (PMID 32686903, 2020). "Interestingly, when HGF inhibition was combined with c-MET inhibition and chemotherapy (triple therapy) in mouse models of early and advanced PC, a significant inhibitory effect was observed on cancer metastasis." (PMID 33271944, 2020). "In addition to the CTCs analysis, we demonstrated the ddPCR approach to be a useful tool for detecting MET amplification in plasma samples from cancer patients." (PMID 32102486, 2020). "It is widely known that EGFR and MET stimulate invasion of cancer cells." (PMID 31649529, 2019). "Specifically, MET amplification, BRAFV600E mutation or hotspot mutations involving KRAS have been shown to emerge in tumour and/or plasma samples from patients with TRK fusion-positive cancers that have progressed on a TRK inhibitor." (PMID 31738426, 2019). "MET, the receptor of hepatocyte growth factor, was identified as a cancer stem cell marker in PDAC." (PMID 31311829, 2019). "This work argues for the importance of further investigation into MET amplification in these cancers, as it could have therapeutic implications for patients who are refractory to standard therapy." (PMID 31040922, 2019). "Consequently, these anti-MET bivalent antibodies are biologically inhibitory for cancer cell migration and invasion." (PMID 30760737, 2019). "Thus MET is most likely involved in mediating therapy resistance in cancer cells through promoting survival of cells exhibiting stem cell-like properties." (PMID 30700325, 2019). "The subnetwork also included MET, another well-known oncogene, and is enriched for members of the Ras signaling pathway, which is also known for its role in oncogenesis and mediating cancer phenotypes such as overproliferation." (PMID 30978274, 2019). "It is well known that HGF/c-MET signaling activates MAPK cascades enhancing cancer cell proliferation and Akt cascades increasing the anti-apoptotic effects, which could eventually increase the drug tolerance capacity in various cancers." (PMID 30680600, 2019). "There was wide aberrant RON and MET expression in the cancer tissues." (PMID 31867280, 2019). "MET has also been reported in many cancers to be localized into the nucleus." (PMID 30700325, 2019). "The recognised ability of cancer-relevant, MET-independent signalling routes to activate FAKs make this kinase family, or druggable targets downstream of it, potentially more attractive therapeutic targets than MET for use in combination with CDK4/6 inhibition." (PMID 31296956, 2019). "Mimicking of a 3D cell niche has been revealed also useful to maintain stem properties of pluripotent stem cells: interestingly c-MET has been indicated as a marker of normal (liver, mammary gland, nervous tissue, gut epithelium) and cancer (breast, brain, colon, pancreas, AML) stem cells." (PMID 30642077, 2019). "It is generally accepted that MET-amplified cancer cells are highly sensitive to MET inhibitors." (PMID 31040922, 2019). "Activation of the MET/FAK axis is known to arise through cancer extrinsic and intrinsic cues." (PMID 31296956, 2019). "The MET-mediated down-regulation of co-stimulatory molecules and up-regulation of co-inhibitory molecules, particularly PD-L1, in cancer cells suggests that MET may contribute to the immune evasion of cancer cells." (PMID 31480591, 2019). "c-MET has been reported to inhibit apoptosis in cancer cells and induce chemotherapy resistance." (PMID 31766284, 2019). "This method, which could be used for high throughput pharmacological screenings, shows that c-MET inhibitors, different from cytotoxic agents such as gemcitabine and oxaliplatin, can be effective against cancer cell growth in the presence of PSCs." (PMID 31072019, 2019).
cancer (continued). "Therefore, high c-MET expression and involvement of HGF/c-MET pathway has been observed in a large part of cancer and has been correlated with poor patient survival." (PMID 30642077, 2019). "Because of the strong association between HGF/c-MET activation and human cancers, targeting HGF/c-MET by miRNAs may be a promising approach for cancer treatment." (PMID 30360560, 2018). "Further investigation of the miRNA-HGF/c-MET may supply effective and promising therapy in human cancers, including digestive system cancers." (PMID 30360560, 2018). "Thus far, published case reports have only described treatment response with single agent MET-targeting kinase inhibitor in cancer patients with tumors bearing MET exon 14 skipping." (PMID 29188469, 2018). "Since HCC827 cells express EGFR activating mutant, which dominantly controls pro‐survival Akt signal, cigarette smoke may only switch the oncogene addition from the EGFR to MET pathway in wtEGFR‐expressing NSCLC cancer cells." (PMID 29570930, 2018). "In addition, c-MET is a well-known proto-oncogene involved in the onset and progression of various human cancers." (PMID 30159127, 2018). "Excessive MET activation promotes the growth, survival, and migration of cancer cells." (PMID 30227653, 2018). "Therefore, activation of pro-HGF in the MET signaling axis is of significant importance in cancer progression, providing a rationale for targeting pro-HGF activation systems in anti-MET treatment." (PMID 30469509, 2018). "However, it has been shown that cancers are able to develop resistance towards these drugs, which in turn can lead to an increase in expression of hepatocyte growth factor receptor MET, the only known receptor for HGF." (PMID 30347815, 2018). "Therefore, finding effective c-MET inhibitors and understanding the regulation of HGF/c-MET pathway are crucial for further inhibiting prolonged activation of this pathway in human cancers, including digestive system cancers." (PMID 30360560, 2018). "MET amplification was also shown to promote resistance towards anti-cancer drugs in SCLC." (PMID 30134579, 2018). "Given that the HGF/c-MET signaling is involved in several processes underlying tumorigenesis, inhibition of this pathway is an obvious therapeutic approach against c-MET-expressing cancers such as NSCLC." (PMID 29725606, 2018). "New drug developments for c-MET inhibitors offer the potential for better cancer treatment." (PMID 30360560, 2018). "The c-MET gene locates on 7q21-31 and encodes a tyrosine kinase Deregulation of HGF/c-MET signaling pathway due to mutation, amplification, overexpression, or activation has been observed in many types of cancers." (PMID 29416799, 2018). "Interestingly, RANBP9 has been shown to interact with oncogene c-MET, a key regulator in development and cancer stem cells." (PMID 30205839, 2018). "In addition to proliferation and angiogenesis, MET activation is known to promote cancer invasion and metastasis." (PMID 30208970, 2018). "Next, we investigated whether mTAMs could directly influence the colonization of cancer cells by regulating epithelial plasticity since accumulated evidence supports the role of MET in metastatic colonization." (PMID 30218063, 2018). "HGF/c-MET signaling mobilizes neutrophils in response to cancer immunotherapies." (PMID 30400835, 2018). "Amplification of MET expression in some cancers would affect interaction of HGF with proteins in the senescence-associated secretory phenotype, as would the stage of angiogenesis in the growth, carcinogenesis and metastasis of tumors in response to Sema3A signaling." (PMID 29854302, 2018). "Moreover, the MET/HGF axis is involved in the crosstalk between cancer cells and the surrounding microenvironment." (PMID 30544501, 2018). "Thus, the Hs746t cancer model resembles approximately 15% of the tumors reported in the literature bearing MET exon 14 skipping that have concurrent MET amplification." (PMID 29188469, 2018).
cancer (continued). "And synergistic combination of drugs with c-MET inhibitors may be promising therapeutic strategies in treating human cancers, including PDAC." (PMID 30360560, 2018). "This approach could be effective not only in RAS-mutant-driven cancers but also those driven by mutations in EGFR, and, by extension, possibly in tumors driven by other upstream receptor tyrosine kinases, such as MET and ALK." (PMID 30590030, 2018). "Bivalent antibodies have also been designed to target MET-expressing cancers." (PMID 29725606, 2018). "It is able to target E2F Transcription Factor 3 (E2F3), DNA methyltransferase 1 (DNMT1), met proto-oncogene (MET) and Rapamycin-insensitive companion of mTOR (Rictor) and in EC cells it seems to be down-regulated through CpG hypermethylation, promoting cancer development and progression." (PMID 30037059, 2018). "The MET gene has increased expression in a variety of cancers when compared to healthy tissues." (PMID 30143666, 2018). "Hypothetically assuming that miR-31 regulates c-MET in cancer cells thus to participate in determining metastatic spread, such a regulation process may only take place in single clones that initiate metastasis formation." (PMID 29463215, 2018). "Accordingly, immunoblot analysis of patient LC26 demonstrated the presence, in cancer tissue, of an abnormal MET protein with lower molecular weight that was expressed at increased levels, compared with the MET protein expressed in the corresponding normal tissue of the same patients." (PMID 29854313, 2018). "As c-MET is an active participant in tumorigenesis and the malignant progress, the assessment of c-MET activation status in real time could be valuable for diagnosis and monitoring of responses to targeted therapies in cancer in the future." (PMID 28485003, 2017). "Altogether, our results indicate that BsAb inhibits HGF-mediated proliferation, migration, and antiapoptosis effects in cancer cells, and could serve as an inhibitory c-MET antibody." (PMID 28404966, 2017). "c-MET and its ligand hepatocyte growth factor are often dysregulated in human cancers." (PMID 28315949, 2017). "However, constitutive activation of the HGF/MET signaling pathway promotes the growth and survival of cancer cells and stimulates their metastatic spread." (PMID 28420162, 2017). "Some cancer cells produce HGF which stimulates MET in an autocrine manner." (PMID 28420162, 2017). "We previously showed that MET activation could be induced during cancer cell proliferation, and could enhance migratory and invasive abilities without affecting cellular sensitivity to the drug." (PMID 28938595, 2017). "Here, we designed and synthesized a bispecific antibody (BsAb) that can bind cellular-mesenchymal to epithelial transition factor (c-MET, overexpressed in several human solid tumor), and programmed death-1 (PD-1, involved in cancer cell immune evasion) with high affinity and specificity." (PMID 28404966, 2017). "In addition, binding of HGF to c-MET increases production of uPA in cancer cells, which further activates precursor HGF to active HGF, thus forming a feed forward loop." (PMID 29100344, 2017). "For instance, in primary cancers retaining SOCS1 expression, MET mutations might allow escape from SOCS1-mediated regulation." (PMID 28235401, 2017). "Perhaps MET mutations control some aspect of cancer biology that was not measured in this and the other preclinical studies that have been performed to date." (PMID 28881678, 2017). "In our opinion, after clinical application of GE-137 with encouraging results for detection of malignant polyps, the field of c-MET-targeted molecular imaging will hopefully become established in the clinic with many expected research results in preclinical studies." (PMID 28485003, 2017).
cancer (continued). "Monoclonal antibodies interfering with the signalling of the hepatocyte growth factor receptor encoded by the MET oncogene and of the epidermal growth factor receptor (EGFR) encoded by the HER1 gene have received approval for the treatment of various types of cancers." (PMID 28182330, 2017). "The role of the HGF/c-MET pathway in PSC-cancer cell interactions was determined by performing indirect co-culture experiments and assessing the effects of PSC secretions on cancer cell functions in the presence or absence of HGF/c-MET inhibitors and/or gemcitabine." (PMID 29100344, 2017). "Molecular imaging is a noninvasive method that can provide accurate information in vivo and in real time, and its application for detecting c-MET activation could represent a breakthrough in cancer diagnosis." (PMID 28485003, 2017). "These cancers are highly aggressive and metastatic, and upregulation of mesenchymal biomarkers is observed in metastases compared to primary tumors, suggesting that these tumors metastasize via an MET‐independent route." (PMID 28548345, 2017). "MET importance on carcinogenesis is becoming so evident that, nowadays, multiple studies are evaluating the efficacy of TKIs (like crizotinib and foretinib) on cancers with MET overexpression." (PMID 29094049, 2017). "However, the molecular mechanisms by which pathways promote BsAb-mediated degradation of c-MET protein require further clarification in cancer cells." (PMID 28404966, 2017). "This suggests that inhibition of MET caspase cleavages could be involved in MET deregulation in cancers." (PMID 28061464, 2017). "Since the discovery of c-MET in the 1980s, the c-MET pathway has gained considerable interest related to a variety of cancers due to the diversity of the cellular responses that follow c-MET activation, including cell growth, survival, motility, invasion, and metastasis." (PMID 28407694, 2017). "Notably, Poloppin and Poloppin-II sensitize mutant KRAS-expressing cancer cells to inhibition of the tyrosine kinase receptor c-MET." (PMID 28807782, 2017). "Since PI3K-associated signaling was shown to control drug efflux transporter BCRP levels in cancer cells, miR-206-induced c-MET/EGFR inhibition might affect BCRP in our cell system." (PMID 29291022, 2017). "We show here that MET inhibition in HSP27‐silenced cells was also associated with the increase in BAK and BAX proteins, whose increased levels have been correlated with better responses of cancer cells to chemotherapy." (PMID 28182330, 2017). "These clinical studies give rise to an idea that the effect of pazopanib on cancers with active HGF/c-MET signalling might be limited." (PMID 28511645, 2017). "However, hPSC-induced cancer cell proliferation was significantly inhibited by the combination of AMG102+c-MET inhibitor." (PMID 29100344, 2017). "Interestingly, three of the 29 subtype-specific ceRNA hubs, namely EGFR, IL6ST and MET, are listed in the Cancer Gene Census of the COSMIC database." (PMID 28052038, 2017). "In addition, several different cancer cell lines bearing mutant oncogenic KRAS were sensitized by 2- to 4-fold to Poloppin after depletion of c-MET using siRNA." (PMID 28807782, 2017). "Thus, while HGF (or fibroblasts) do not further stimulate MET signaling or promote the viability in MET-amplified cancer cells, our results established that MET-amplified NSCLC cells become addicted to HGF upon pharmacological MET inhibition." (PMID 28968967, 2017). "Mutations or fusions of both EGFR and ALK may be primary causes of cancer, whereas both the EGFR gatekeeper mutant T190M and MET may generate drug resistance." (PMID 29086093, 2017). "The protooncogene c-MET is a potential therapeutic target for cancers." (PMID 28077801, 2017).
cancer (continued). "Meanwhile, MACC1 could be bound to the promoter of the MET gene and activate the HGF/MET signaling pathway to promote cancer cell proliferation, invasion, and metastasis." (PMID 27793161, 2016). "Among these compounds with new scaffolds having different quinazoline, pyridine and tetrahydro-pyridothienopyrimidine head groups, compound 11c, 11i, 13b, 13h exhibited both potent inhibitory activities against c-MET and high anticancer activity against tested cancer cell lines in vitro." (PMID 27187326, 2016). "MET and HGF alterations are indeed associated with clinical outcome, metastasis, invasion and disease severity in human cancers, and identification of patients with specific alterations may be critical to predict clinical response to targeted therapies." (PMID 27013592, 2016). "Both the MET and Src tyrosine kinases have been well known as drivers of carcinogenesis and development of resistance to therapies in many cancers including the TNBCs, and pre-clinical and clinical studies investigating benefits of MET or Src targeting have also been recently reported." (PMID 27687593, 2016). "We hypothesize that ABT-700 might be effective in treating cancers harboring amplified MET and focused preclinical studies to assess its antitumor activity in models driven by MET amplification." (PMID 26879245, 2016). "MET encodes for the tyrosine kinase of the hepatocyte growth factor receptor; stable overexpression of MET results in the conversion of primary human osteoblasts into OS cells, demonstrating that MET is pro-tumorigenic and necessary for the induction of a cancer phenotype." (PMID 27851822, 2016). "Thus, it is conceivable that a number of studies have demonstrated MET gene amplification as a potential biomarker to estimate patients with cancers who will benefit from the treatment with selective MET inhibitors or antibodies." (PMID 26765781, 2016). "Similarly, although MET kinase inhibitors curb the growth of leukemic cells that are addicted to HGF/MET signaling, cancer cells rapidly develop resistance to MET kinase inhibitors due to compensatory upregulation of HGF." (PMID 27121052, 2016). "Additionally, MET-driven or MET-positive cancer should be determined by the dominant activation of MET and related oncogenic pathways." (PMID 27013592, 2016). "HGF-producing cancer cells display autocrine activation of MET signaling." (PMID 27121052, 2016). "Because ddPCR could accurately evaluate the MET copy number in cancer cell lines, we then determined whether ddPCR could detect the presence of MET amplification and compared the results to those obtained from FISH." (PMID 26765781, 2016). "The behavior of MET immunoreactivity across the remaining 179 cancer surfaces, was visualized by displaying corresponding percentages of MET positive – moderate to strong immunoreactivity – cancer cells in the center and periphery as data points in a scatter plot." (PMID 26909606, 2016). "Amplification of MET in human cancer tissues can be identified by FISH." (PMID 26879245, 2016). "When comparing the membranous and cytoplasmic immunoreactivities obtained under FFPE conditions, the observed intensities indicate that CVD13 was most sensitive in the detection of cytoplasmic MET and D1C2 was most sensitive in the detection of membranous MET in FFPE cancer cells and tissues." (PMID 26909606, 2016). "Notably, MET amplification-driven cancer cells (EBC-1, NCI-H1993, MKN-45 and SNU-5) were most sensitive to Simm530 treatment, with IC50 values of 0.7, 0.8, 0.9 and 0.7 nM, respectively." (PMID 27191264, 2016). "Together with MACC1-regulating cancer growth via the activation of the HGF/c-MET/PI3K/AKT signaling pathway, we purposed that MACC1 might induce trastuzumab resistance by regulating the Warburg effect via the PI3K/AKT signaling pathway." (PMID 27581375, 2016). "The aberrant MET signaling has been regarded as a robust target in the anti-cancer therapy." (PMID 26765781, 2016).